GOLGA6L10 (golgin A6 family like 10)
Synonyms: GOLGA6L18
Tractability: PROTAC: ubiquitination databases record sites on it.
Gene: Protein-coding gene on chromosome 15 (82,339,993 to 82,349,475, reverse strand). Ensembl gene ENSG00000278662.
Genetic constraint (gnomAD): Loss-of-function variants: 4 observed, 22.3 expected, observed/expected ratio (o/e) 0.18, 90% interval 0.087 to 0.41. The synonymous counts are far from expectation, so gnomAD's model fits this gene poorly and the ratio says little. Missense variants: 27 observed, 225.57 expected, observed/expected ratio (o/e) 0.12, 90% interval 0.087 to 0.17. Synonymous variants: 9 observed, 87.19 expected, observed/expected ratio (o/e) 0.1, 90% interval 0.061 to 0.18.
Homologues: Paralogues in human: GOLGA6L4 (96% identical), GOLGA6L9 (82% identical), GOLGA6L6 (27% identical), GOLGA6L22 (27% identical), GOLGA6L1 (26% identical), GOLGA6L26 (26% identical), GOLGA6L2 (26% identical), GOLGA6L24 (26% identical), GOLGA6L25 (26% identical), GOLGA6L7 (24% identical).
Diseases named in the same sentence as GOLGA6L10 in open-access papers:
GOLGA6L10 is named in the same sentence as 1 disease in open-access papers, as found by Europe PMC text mining. Sharing a sentence is not in itself a finding about the gene and the disease. The quoted sentences say what the papers report.
tumor (1 paper, 2013). "Only four SNVs in two genes, KRT4 and GOLGA6L10, were identified, resulting in the WTS and CNV data driving the biological narrative on this tumor." (PMID 24204627, 2013).